SLC2A1 (solute carrier family 2 member 1)
Diseases named in the same sentence as SLC2A1 in open-access papers (continued):
Sharing a sentence is not in itself a finding about the gene and the disease.
osteonecrosis (3 papers, 2021 to 2023). A none disease characterized by death of bone tissue due to a lack of blood supply. "It was experimentally verified that both PNP and SLC2A1 were significantly downregulated in the peripheral blood of SONFH patients, as well as in the hormonal osteonecrosis samples, which was consistent with the results of our bioinformatics analysis." (PMID 36979852, 2023). "In addition, the abolition of PI3K/AKT signaling induced by miR-186 may contribute to the pathogenesis of non-traumatic osteonecrosis, while miR-186 targets the 3′ UTR of Glut1 (SLC2A1)." (PMID 33451334, 2021).
placental insufficiency (3 papers, 2013 to 2021). Failure of the placenta to deliver an adequate supply of nutrients and oxygen to the fetus. "In the present study, placental insufficiency could be explained, at least in part, by decreased placental mRNA expression of SLC2A3, a gene encoding a glucose transporter, GLUT-3, although mRNA expression of SLC2A1, which encodes for GLUT-1, did not change by ET." (PMID 33244103, 2020).
schizophrenia (3 papers, 2014 to 2024). A major psychotic disorder characterized by abnormalities in the perception or expression of reality. "In the lactate shuttle, six (55%) of the significantly altered genes (n = 11) were upregulated: GLUL, LDHC, SLC16A3, SLC1A2, SLC1A3, and SLC2A1, which were collectively expressed in schizophrenia groups at a level of 1.5× higher than in control groups (LFC = 0.58)." (PMID 39125835, 2024).
Adult onset (2 papers, 2025). Onset of disease manifestations in adulthood, defined here as at the age of 16 years or later. "Two unrelated patients with adult‐onset cervical dystonia, one also involving the upper limbs and shoulders, carried a novel SLC2A1 variant (p.Gln25Lys)." (PMID 40533913, 2025).
atopic dermatitis (2 papers, 2020 to 2023). "While we were screening a molecular target for atopic dermatitis, we found the levels of glucose transporters including Glut1 (SLC2a1) and Glut3 (SLC2a3) are highly expressed in skin biopsies of dermatitis patients from multiple datasets." (PMID 31991554, 2020).
Barrett esophagus (2 papers, 2018 to 2022). Esophageal lesion lined with columnar metaplastic epithelium which is flat or villiform. "SLC2A1 encodes the membrane protein Glucose Transporter 1 (GLUT1) and high expression of GLUT1 has been associated with poor survival in oesophageal squamous cell carcinoma and progression of Barrett's oesophagus to adenocarcinoma but GLUT1 has not been studied as a prognostic marker in OAC." (PMID 29719622, 2018).
cervical dystonia (2 papers, 2022 to 2025).
chronic kidney disease (2 papers, 2024). Impairment of the renal function secondary to chronic kidney damage persisting for three or more months. "The interaction of SLC2A1 may influence the onset of chronic kidney disease by regulating ferroptosis." (PMID 38517368, 2024).
CLIFAHDD syndrome (2 papers, 2020 to 2021). "All CKD were started in children younger than 3 years, except one SLC2A1 (-)-girl with CLIFAHDD syndrome who started a CKD in another hospital." (PMID 33806661, 2021).
developmental and epileptic encephalopathy (2 papers, 2024 to 2025). An epilepsy associated with developmental impairment that may be due to either the underlying etiology or the superimposed epileptic activity, or both. "The SLC2A1 gene encodes the glucose transporter type 1 (GLUT1), and pathogenic variants lead to a broad spectrum of neurological disease, including developmental and epileptic encephalopathy." (PMID 38921008, 2024).
diabetic cardiomyopathy (2 papers, 2014). Diabetic cardiomyopathy is a disorder of the heart muscle in people with diabetes. "Our molecular analysis showed increased levels of Cxadr, Il6st, Pdgfra, and Slc2a1 in the LV of both Wt and Hif1a+/- diabetic hearts which corresponds to the onset of pathological processes associated with cardiac remodeling in diabetic cardiomyopathy." (PMID 24502509, 2014).
hemiplegic migraine (2 papers, 2016 to 2022). "An AHC patient showing a mutation in SLC2A1 p.Gly18Arg, which leads to the loss of GLUT1 expression, was also diagnosed with hemiplegic migraine, which can be related to increases in cortex glutamate levels." (PMID 27313535, 2016).
hyperlipidaemia (2 papers, 2022 to 2024). "Linear regression analysis controlling for sex, hyperlipidaemia, CCIMT and CKD stage, showed that two SNPs in SLC2A1 (coding for the GLUT1 transporter), rs841848 and rs710218, and the rs3813008 variant in SLC5A2 (coding for SGLT2) were associated with eGFR values." (PMID 36314849, 2022).
intestinal cancer (2 papers, 2013 to 2024). "The spatial visualization of SLC2A1 gene expression in intestine cancer spatial transcriptomics data showed a non-uniform distribution in the tissue and SLC2A1 (GLUT1) expression tended to colocalize with regions that had small blood vessels penetrating the tumor." (PMID 39678375, 2024).
mastitis (2 papers, 2017 to 2024). Inflammation of breast tissue during lactation or postpartum due to an obstructed duct or infection. "Several of the genes downregulated in Yakutian cattle were related to the susceptibility of a host to diseases, including Mycobacterium avium paratuberculosis, bovine tuberculosis, mastitis, brucellosis, and bovine respiratory disease (CD209, EEF1A2, SLC2A1)." (PMID 39333243, 2024). "The numerically-greater expression of SLC2A1 and LDHA in INO cows during the study could indicate that these cows were more immuno-compromised because a previous study detected marked upregulation of LDHA in PMNL after a mastitis challenge." (PMID 28469842, 2017).
Nystagmus (2 papers, 2015 to 2020). Rhythmic, involuntary oscillations of one or both eyes related to abnormality in fixation, conjugate gaze, or vestibular mechanisms. "In addition there was evidence of reduced penetrance in SLC2A1, most clearly in the family with the p.T60M mutation that presented with paroxysmal attacks, headaches and nystagmus where the father and brother had the mutation but were unaffected (see family tree)." (PMID 26598494, 2015).
overnutrition (2 papers, 2017 to 2021). An imbalanced nutritional status resulting from excessive intake of nutrients. "In the case of maternal overnutrition, downregulation of SLC2A1 in the YS membrane presumably helps prevent the embryo from being oversupplied with glucose." (PMID 34573470, 2021).
pituitary adenoma (2 papers, 2020 to 2023). "SLC2A1 was significantly associated with the invasiveness of pituitary adenoma in the GSE169498 microarray." (PMID 36936141, 2023). "In conclusion, SLC2A1 expression is associated with the invasiveness of pituitary adenoma." (PMID 36936141, 2023). "SLC2A1 is significantly upregulated in invasive pituitary adenoma with satisfactory predictive value." (PMID 36936141, 2023). "We used immunohistochemical staining to detect SLC2A1 expression in non-invasive and invasive pituitary adenomas." (PMID 36936141, 2023). "Proteomics data and experiments verified that SLC2A1 was significantly upregulated in invasive pituitary adenomas." (PMID 36936141, 2023). "SLC2A1 expression was significantly higher in invasive pituitary adenomas than in non-invasive pituitary adenomas, the difference was statistically significant (P<0.05)." (PMID 36936141, 2023). "The final experiment revealed that SLC2A1 was significantly upregulated in invasive pituitary adenoma." (PMID 36936141, 2023). "SLC2A1 was significantly correlated with the invasiveness of pituitary adenoma, and the ROC curve was satisfactory." (PMID 36936141, 2023). "This was consistent with our quantitative proteomics and GSE169498 analysis, suggesting that SLC2A1 may be a potential biomarker of invasion for pituitary adenoma." (PMID 36936141, 2023). "In addition, the differential expression of SLC2A1 in invasive pituitary adenomas was experimentally verified." (PMID 36936141, 2023). "In our study, SLC2A1 was significantly overexpressed in invasive pituitary adenomas, but the exact mechanism by which SLC2A1 promotes the progression of pituitary adenomas remains unknown." (PMID 36936141, 2023). "SLC2A1 is a potential biomarker and therapeutic target for invasion of pituitary adenomas." (PMID 36936141, 2023). "SLC2A1, CLDN4, LAMC2, S100A4, and ITGB3 were significantly correlated with the invasiveness of pituitary adenoma (P<0.05)." (PMID 36936141, 2023). "As SLC2A1 was similarly correlated with invasion in proteomics and GSE169498 microarrays, it may be a potential marker for invasion in pituitary adenoma." (PMID 36936141, 2023).
pneumonia (2 papers, 2024 to 2025). An acute, acute and chronic, or chronic inflammation focally or diffusely affecting the lung parenchyma, caused by an infection in one or both of the lungs (by bacteria, viruses, fungi, or mycoplasma.). "We infected Slc2a1-ΔM and Slc2a1fl/fl cre-negative littermate control mice with viable S. pneumoniae serotype 2 (D39) via the airways, resulting in pneumonia (12 h after inoculation) with subsequent dissemination of the infection to distant organs (42 h after inoculation)." (PMID 41226500, 2025).
tongue squamous cell carcinoma (2 papers, 2019 to 2023). A squamous cell carcinoma that arises from the tongue. "For instance, SLC2A1 was overexpressed in tongue squamous cell carcinoma compared to normal tissue, with an FC of 4.612 (p = 8.20E-8)." (PMID 37542344, 2023).
uterine corpus endometrial carcinoma (2 papers, 2022 to 2025). A endometrial carcinoma (disease) that involves the body of uterus. "Based on these findings, SLC2A1 and MPST may serve as diagnostic markers for uterine corpus endometrial carcinoma (UCEC)." (PMID 40746529, 2025). "Nevertheless, the role of SLC2A1 in uterine corpus endometrial carcinoma (UCEC) remains not fully understood." (PMID 40746529, 2025). "However, the specific roles of SLC2A1 and MPST in tumor immune cell infiltration, abnormal DNA methylation, and prognosis in uterine corpus endometrial carcinoma (UCEC) have not yet been elucidated." (PMID 40746529, 2025).
bladder urothelial carcinoma (1 paper, 2020). "For example, we performed survival analysis using mRNA (SLC2A1) as a biomarker in bladder urothelial carcinoma (n=403)." (PMID 32369034, 2020).
dermatitis (1 paper, 2020). An inflammatory process affecting the skin. "We determined the expression levels of glucose transporters Glut1 (SLC2a1) and Glut3 (SLC2a3) in skin biopsies of dermatitis patients and control subjects from several datasets." (PMID 31991554, 2020).
ductal breast carcinoma (1 paper, 2021). "In the Richardson Breast 2 dataset, SLC2A1 was also overexpressed in ductal breast carcinoma with a fold change of 2.340." (PMID 34525987, 2021).
endometritis (1 paper, 2021). An acute or chronic, usually bacterial infectious process affecting the endometrium. "Similarly, expressions of IFNT, ISG15, CXCL10, PPARG, RXRG, SLC2A1, and SLC27A6 proteins were greater and MUC1 was lower in the endometrium of cows without endometritis compared with cows with endometritis (p < 0.05)." (PMID 33920430, 2021).
energy metabolic disorders (1 paper, 2022). "Although the depletion of miRNA or target genes both resulted in energy metabolic disorders, whether these metabolic phenotypes under antagomiR treatment were caused by increased expression of SLC2A1 and GLIS2 remains unclear." (PMID 36197879, 2022).
femoral head osteonecrosis (1 paper, 2021). "Another study showed that miR-140-5p may contribute to the development femoral head osteonecrosis via ubiquitin proteasome system, while SLC2A1 was a target of miR-140-5p." (PMID 33451334, 2021).
focal epilepsy (1 paper, 2020). A seizure caused by a localized disorder. "In addition, mutations in GLUT1 (also known as SLC2A1) can also cause a syndrome called focal epilepsy (FE) and paroxysmal exercise-induced dyskinesia (PED), whose attacks may be associated with increased glucose consumption caused by exercise." (PMID 33363507, 2020).
hematoma (1 paper, 2025). A hematoma is a collection of blood from a vascular structure into an extravascular space. "In the brain tissue of patients who developed CVS following a cerebral hemorrhage, CDK6 and SLC2A1 showed upregulation in the hematoma region, where they co-localized with SMA (smooth muscle actin)." (PMID 39981435, 2025).
hereditary spastic paraplegia (1 paper, 2021). Hereditary spastic paraplegias (HSP) comprise a genetically and clinically heterogeneous group of neurodegenerative disorders characterized by progressive spasticity and hyperreflexia of the lower limbs.
Neonatal hypoglycemia (1 paper, 2025). "Given that seizures are the most common clinical manifestation of neonatal hypoglycemia, the association of lower SLC2A1 transcript levels in CM in comparison to SMA suggests that hypoglycorrhachia may underlie some of the seizures and loss of consciousness seen in CM51." (PMID 40383794, 2025).
non-alcoholic fatty liver disease (1 paper, 2024). "Studies on SLC2A1 indicate that its down-regulation in non-alcoholic fatty liver disease can promote lipid accumulation." (PMID 39061594, 2024).
Onset (1 paper, 2025). The age group in which disease manifestations appear. "Deficiency of the Glut1 transporter due to mono‐allelic variants in SLC2A1 causes hypoglycorrhachia, resulting in a neurological spectrum from neonatal epilepsy to adult‐onset paroxysmal movement disorders (PMD)." (PMID 39830115, 2025).
ovarian dysfunction (1 paper, 2025). The inability of the ovaries to function. "Notably, intersection of the DEG datasets across all timepoints revealed two consistently altered genes, Cdh13 and Slc2a1, highlighting them as potential key mediators of IVF-associated ovarian dysfunction and accelerated reproductive aging." (PMID 41278955, 2025).
paroxysmal dystonia (1 paper, 2021). "For example, a heterozygous missense variant in the SLC2A1 gene, encoding glucose transporter 1 (GLUT1) that is responsible for the entry of glucose into the brain, may cause a complex phenotype including paroxysmal dystonia due to the reduced levels of glucose in the CNS." (PMID 33876307, 2021).
pneumococcal pneumonia (1 paper, 2025). A febrile disease caused by STREPTOCOCCUS PNEUMONIAE. "Strikingly, Slc2a1-ΔM mice demonstrated an unaltered host response during pneumococcal pneumonia in vivo as compared to littermate control mice, with the sole exception of enhanced bacterial dissemination to the spleen at 12 h post-infection." (PMID 41226500, 2025). "Thus, Slc2a1-ΔM mice had an unaltered host response during pneumococcal pneumonia, except for more frequent bacterial dissemination to the spleen early after infection." (PMID 41226500, 2025).
retinoblastoma (1 paper, 2022). A malignant tumor that originates in the nuclear layer of the retina. "SLC2A1 expression was associated with common tumor biological function in UVM, KIRC, and retinoblastoma (RB) to varying degrees." (PMID 36712872, 2022).
septic arthritis (1 paper, 2022). "As the physiological symptoms of septic arthritis worsened with greater MRSA bioburden, the mRNA expression of Slc2a1 and Slc16a3 increased, and expression levels slightly decreased over time, but still remained higher than normal." (PMID 36354099, 2022).
thrombosis (1 paper, 2021). "In a recent study, RNA sequencing in granulocytes of PV patients documented higher expression levels of F3, SELP, VEGFA, and SLC2A1, that were directly correlated with JAK2 expression and JAK2V617F allele burden in patients with a history of thrombosis." (PMID 34897288, 2021).
Uterine leiomyoma (1 paper, 2022). The presence of a leiomyoma of the uterus. "In uterine leiomyoma, SLC2A1 and ALDOA were identified as HIF-1α-responsive genes." (PMID 35404841, 2022).
uterine serous carcinoma (1 paper, 2022). "The alteration frequency of SLC2A1 (9.17% of 109 cases) was the highest in uterine serous carcinoma." (PMID 36712872, 2022).